CEACAM1 (CEA cell adhesion molecule 1)
Diseases named in the same sentence as CEACAM1 in open-access papers (continued):
Sharing a sentence is not in itself a finding about the gene and the disease.
benign ovarian tumors (1 paper, 2020). "Using LASSO regression, a multiplex model including 6 biomarkers (HE4, CA125, ITGAV, CXCL1, CEACAM1, IL-10RB) and age had the highest diagnostic accuracy for discrimination between benign ovarian tumors and EOC including borderline tumors." (PMID 33075095, 2020).
brain cancer (1 paper, 2008). A primary or metastatic malignant neoplasm affecting the brain. "Since very little is known about the role of CEACAM1 in brain cancer, we also examined the expression of CEACAM1 in three human malignant glioma cell lines, U87MG, U251T and T98G." (PMID 18507857, 2008).
Burkitt lymphoma (1 paper, 2025). A rare form of malignant mature B-cell non-Hodgkin lymphoma. "Similarly, overexpression of CEACAM1 in the CEACAM1-negative Burkitt lymphoma cell line ST486 did not affect the IgM surface expression but significantly downregulated SYK activation following BCR stimulation compared to control cells." (PMID 40436855, 2025).
Cerebral ischemia (1 paper, 2022). Restriction of arterial blood supply to the brain associated with insufficient oxygenation to support the metabolic requirements of the tissue. "The results implied that CEACAM1 may serve as an inhibitory regulator affecting the progression of focal cerebral ischemia, especially involved in the BBB injury progress." (PMID 35657334, 2022). "This demonstrated that CEACAM1 may inhibit the neutrophil‐mediated tissue damages and breakdown of BBB in focal cerebral ischemia." (PMID 35657334, 2022).
cervical adenocarcinoma (1 paper, 2020). An adenocarcinoma arising from the cervical epithelium. "In contrast, HeLa cells (a cervical adenocarcinoma cell line) lack expression of CEACAM1, 3, 5 and 6, but these cells are sensitive to delivery and phosphorylation of CagA." (PMID 32435278, 2020).
cholestasis (1 paper, 2021). Impairment of the bile flow caused by obstruction within the liver, or outside the liver in the bile duct system. "An increase of serum CEACAM1 level was associated with cholestasis." (PMID 34837908, 2021). "High levels of serum CEACAM1 in our study could be due to the degree of cholestasis or tissue type of the well-differentiated HCC as well." (PMID 34837908, 2021). "This could be explained by the number of patients with early stage HCC where cholestasis may not be severe enough to produce a high level of serum CEACAM1." (PMID 34837908, 2021).
chronic kidney disease (1 paper, 2022). Impairment of the renal function secondary to chronic kidney damage persisting for three or more months. "Higher uptake into the kidneys of Ceacam1−/− mice is also important in that NAFLD accelerates chronic kidney disease." (PMID 36559027, 2022).
cleft palate (1 paper, 2013). Cleft palate is a fissure type embryopathy that affects the soft and hard palate to varying degrees. "Analysis of the CEACAM1 levels in two different genetically modified models with various forms of cleft palate gave us a further indication of how CEACAM1 might be functioning." (PMID 23613893, 2013).
colorectal adenocarcinoma (1 paper, 2023). The most common type of colorectal carcinoma. "Preserving the interactions between CEACAM1 and CEACAM5 might be critical in preventing colorectal adenocarcinomas." (PMID 36741860, 2023). "In two cell lines of HT29 cells (colorectal adenocarcinoma cells), induction of CEA did not affect the low CEACAM1 cell line." (PMID 36741860, 2023).
colorectal tumors (1 paper, 2023). "Restoring CEACAM1 in T cells may prove critical in preventing inflammation and restoring apoptosis, as most colorectal tumors express decreased levels of CEACAM1." (PMID 36741860, 2023).
Cowden syndrome (1 paper, 2018). "Further studies are required to determine the implication of CEACAM1 and MIB2 in the severity of Cowden syndrome in our proband and occurrence of early onset MALT lymphoma in a parent." (PMID 30233642, 2018).
E. coli infection (1 paper, 2019). "As for the eight common genes screened out in all four datasets, CEACAM1, GK, PFKFB3, and TNFAIP6 emerged repeatedly in the S. aureus group, but CEACAM1, IL18RAP, LILRA5, PFKFB3, PSTPIP2, and SOCS3 emerged in the E. coli infection." (PMID 31093495, 2019).
egg allergy (1 paper, 2016). A food allergy that is an allergy or hypersensitivity to dietary substances from the yolk or whites of eggs, causing an overreaction of the immune system which may lead to severe physical symptoms. "Using a combination of differential gene expression and multiplex cytokine measurement, we observed that egg allergy was associated with IL-9, IL-5, and TNFα expression and secretion, as well as expression of CEACAM1, and CISH." (PMID 27788149, 2016).
endometrial tumors (1 paper, 2019). "Increased soluble and surface CEACAM-1 has been associated with endometrial tumors, suggesting that the body responds to both the extrauterine tissue and endometrial tumors in a similar fashion." (PMID 31333337, 2019).
endotoxemia (1 paper, 2025). "Collectively, our results suggest that rhamnose signals via the CEACAM1/LGALS9-p38 axis, which suppresses endotoxemia-associated inflammation, and that rhamnose is a candidate anti-inflammatory agent for the control of infection-induced organ damage." (PMID 40708539, 2025).
gestational diabetes mellitus (1 paper, 2020). "The aim of this study was to estimate the levels of circulating carcinoembryonic antigen-related cell adhesion molecule 1 (CEACAM1) in subjects with gestational diabetes mellitus (GDM) and investigate the relationships between CEACAM1 and GDM." (PMID 32414367, 2020).
head and neck carcinoma (1 paper, 2021). A carcinoma that arises from the head and neck region. "All the current findings suggest that both TIM-3 and CEACAM1 were valuable predicting markers that might provide help for clinicians to design effective immunotherapeutic regimen against head and neck carcinoma." (PMID 34368221, 2021).
heart failure (1 paper, 2016). Inability of the heart to pump blood at an adequate rate to meet tissue metabolic requirements.
Hepatic fibrosis (1 paper, 2024). The presence of excessive fibrous connective tissue in the liver. "This would ascertain a common underlying mechanism of CEACAM1’s prevention of hepatic fibrosis marked by limited off-target effects." (PMID 39640841, 2024). "The data above demonstrate that the loss of CEACAM1 in hepatocytes and endothelial cells constitutes a unifying mechanism underlying hepatic fibrosis in mice independently of metabolic regulation." (PMID 39640841, 2024). "In summary, loss of CEACAM1 in the two most dominant cells in the liver causes hepatic fibrosis with inflammation." (PMID 39640841, 2024). "Thus, we have begun by deleting the Ceacam1 gene individually in murine hepatocytes and endothelial cells (highest and second highest site of CEACAM1 expression, respectively) to evaluate its cell-specific role in the pathogenesis of hepatic fibrosis and delineate the underlying mechanisms." (PMID 39640841, 2024). "For instance, caloric restriction ameliorates MASH phenotype and hepatic fibrosis in rats with low aerobic capacity, partly by inducing their hepatic CEACAM1 expression." (PMID 39640841, 2024). "In keeping with the predominant expression of CEACAM1 in LSECs relative to the general endothelial pool in the liver, LSECs of VECadCre+Cc1fl/fl single, but not VECadCre+Et1.Cc1fl/fl double mutants, manifested cell injury, characteristic of hepatic fibrosis." (PMID 39640841, 2024). "Further studies are needed to explore whether hepatic fibrosis could similarly stem from deleting Ceacam1 in other liver cells such as immune cells." (PMID 39640841, 2024). "Furthermore, hepatic CEACAM1 levels progressively decline with the advancement of hepatic fibrosis stage in patients with MASLD/MASH." (PMID 39640841, 2024). "Moreover, endothelial CEACAM1 expression gradually declined with the advanced hepatic fibrosis stage and in parallel to the progressive increase in plasma Endothelin-1 levels of patients with MASH." (PMID 39640841, 2024). "However, more studies are needed to delineate the independent role of CEACAM1 in other liver cells, such as Kupffer cells, before we could formulate a CEACAM1-based unifying mechanism against hepatic fibrosis." (PMID 39640841, 2024).
Hepatitis B infection (1 paper, 2021). "Hepatitis B infection may influence the expression of CEACAM1." (PMID 34837908, 2021).
infarction (1 paper, 2016). A localised pathological necrosis of tissue resulting from obstruction of the blood supply usually by a thrombus, an embolus, or vascular torsion. "Our study indicates that CEACAM1 exacerbates hypoxic cardiomyocyte injury and post-infarction cardiac remodeling by enhancing cardiomyocyte mitochondrial dysfunction and endoplasmic reticulum stress-induced apoptosis." (PMID 26911181, 2016).
injury (1 paper, 2025). Damage inflicted on the body as the direct or indirect result of an external force, with or without disruption of structural continuity. "Fourth, well-controlled multicenter clinical trials are needed to bridge this gap because our OLT cohort may not have captured the dynamic range of the HuR/Ceacam1 signaling axis in patients with acute liver injury." (PMID 40985895, 2025).
ischemia (1 paper, 2016). A hypoperfusion of the BLOOD through an organ or tissue caused by a PATHOLOGIC CONSTRICTION or obstruction of its BLOOD VESSELS, or an absence of BLOOD CIRCULATION. "Considering that angiogenesis also plays an important role in cardiac remodeling associated with ischemic heart disease, it would be warranted to clarify whether CEACAM1 influences myocardial angiogenesis in an ischemia/reperfusion model." (PMID 26911181, 2016).
kidney stone (1 paper, 2025). "Five of these protein ratio pairs positively promote kidney stone development: BAIAP2/MME protein level ratio, GRPEL1/MME protein level ratio, HLAE/IL15 protein level ratio, CEACAM1/GGT1 protein level ratio and BTN2A1/IL18BP protein level ratio." (PMID 40673688, 2025).
Liver Disease (1 paper, 2018). "In obstructive and inflammatory liver diseases, soluble CEACAM1 is shed into human bile where it can serve as an indicator of liver disease." (PMID 30314283, 2018). "In addition, soluble CEACAM1 is strongly increased in the serum and urine of rats with liver disease." (PMID 30314283, 2018).
lung fibrosis (1 paper, 2022). "In murine bleomycin-induced pulmonary fibrosis, CEACAM1-positive monocytes were involved in lung fibrosis." (PMID 36341379, 2022). "In murine bleomycin-induced lung fibrosis, CEACAM1-positive monocytes infiltrate the interstitium of the lungs and are involved in lung fibrosis." (PMID 36341379, 2022).
MALT lymphoma (1 paper, 2018). An indolent, extranodal type of non-Hodgkin lymphoma composed of small B-lymphocytes (centrocyte-like cells). "The CEACAM1 mutation in the proband was inherited from a parent affected with MALT lymphoma, and may contribute to their lymphoproliferative B cell disease, and was absent from the two healthy persons in this study." (PMID 30233642, 2018).
mantle cell lymphoma (1 paper, 2025). Mantle cell lymphoma is a rare form of malignant non-Hodgkin lymphoma affecting B lymphocytes in the lymph nodes in a region called the ``mantle zone''. "Here, the authors discover that CEACAM1, an immunoglobulin-like transmembrane protein, is essential for a subset of mantle cell lymphoma through activation of the BCR." (PMID 40436855, 2025).
marginal zone lymphoma (1 paper, 2025). A usually indolent mature B-cell lymphoma, arising from the marginal zone of lymphoid tissues. "We also found that CEACAM1 long isoform was predominantly expressed in the marginal zone lymphoma (MZL) cell line Karpas-1718 (K1718) and modestly expressed in the activated B-cell (ABC) DLBCL cell line HBL-1." (PMID 40436855, 2025).
medullary thyroid carcinoma (1 paper, 2017). "Subsequently, we explored other tumor cell lines harboring gain‐of‐function type mutations in tyrosine kinases, and found the expression of CEACAM1 mRNA and protein in a human medullary thyroid carcinoma (MTC) cell line, TT." (PMID 28332308, 2017).
Myocardial fibrosis (1 paper, 2016). "In this study, we noted that loss of CEACAM1 significantly reduced myocardial fibrosis in the non-infarct zone, suggesting that CEACAM1 may influence the development of fibrosis or its degradation." (PMID 26911181, 2016). "However our findings that fibroblasts didn’t express CEACAM1 and lack of CEACAM1 inhibited myocardial fibrosis suggest that CEACAM1 does not induce apoptosis of cardiomyocytes." (PMID 26911181, 2016). "We detected myocardial fibrosis using Masson trichrome staining method, and found that the fibrotic infarct length and fibrosis area in the non-infarct zone were significantly smaller in the CEACAM1 KO-MI group than in the WT-MI group (P < 0.05), suggesting less ventricular expansion in KO mice." (PMID 26911181, 2016).
myocarditis (1 paper, 2023). Myocarditis is a condition that is characterized by inflammation of the heart muscle (myocardium). "Clinically relevant pathways, such as those of the inflammasome in ICI-induced myocarditis or the neutrophil activation cascade in gastrointestinal irAEs, have been identified through the overexpression of type 5 and 6 guanylate binding proteins and CD177 and CEACAM1 genes, respectively." (PMID 36900420, 2023).
myxoma (1 paper, 2024). A benign soft tissue neoplasm characterized by the presence of spindle and stellate cells, lobulated growth pattern, and myxoid stroma formation. "Myxoma tumour cells, including ETCs and MTCs, expressed a relatively high level of genes encoding most immune checkpoint ligands, such as galectin‐3, PD‐L1, VSIG‐3, CD155, CD112 and CEACAM1." (PMID 38318640, 2024).
Neonatal sepsis (1 paper, 2013). Systemic inflammatory response to infection in newborn babies. "The primary finding in this study suggests that late-onset neonatal sepsis in VLBW-infants causes an increase in the percentage circulating CD4+ T-cells expressing CEACAM1." (PMID 23894299, 2013). "Late-onset neonatal sepsis in VLBW-infants was associated with an increased percentage CEACAM1 positive CD4+ T-cells." (PMID 23894299, 2013). "Firstly we tested whether CD4+ T-cell CEACAM1 expression is increased in very low birthweight (VLBW) infants (birth weight 401-1500 gram) with late-onset neonatal sepsis." (PMID 23894299, 2013). "In conclusion our data demonstrate increased surface expression of the co-inhibitory immune receptor CEACAM1 in late-onset neonatal sepsis in VLBW-infants, and increased circulating soluble CEACAM1 in children with meningococcal sepsis." (PMID 23894299, 2013). "In conclusion our data demonstrate increased surface expression of the co-inhibitory immune receptor CEACAM1 in late-onset neonatal sepsis in VLBW-infants, and increased circulating CEACAM1 self-ligand soluble CEACAM1 in children with meningococcal sepsis." (PMID 23894299, 2013). "In the VLBW infants with late-onset neonatal sepsis CEACAM1 expression on the CD4+ T-cells correlated with the maximal CRP levels, while in children with meningococcal septic shock serum soluble CEACAM1 concentrations did not correlate with CRP." (PMID 23894299, 2013).
non-Hodgkin lymphoma (1 paper, 2021). Distinct from Hodgkin lymphoma both morphologically and biologically, non-Hodgkin lymphoma (NHL) is characterized by the absence of Reed-Sternberg cells, can occur at any age, and usually presents as a localized or generalized lymphadenopathy associated with fever and weight loss. "We have demonstrated the over expression of CEACAM1 in WM vs. IgM MGUS and vs. CTRLs B-cells, confirming previous investigations which showed the up regulation of CD66a in bone marrow samples of non-Hodgkin lymphoma (NHL) and MM." (PMID 33921415, 2021).
pancreatic ductal adenocarcinoma (1 paper, 2026). An infiltrating adenocarcinoma that arises from the epithelial cells of the pancreas. "We evaluated a three-marker model comprising serum CA19-9 in combination with the plasma proteins ITIH3 and CEACAM1 for pancreatic ductal adenocarcinoma (PDAC) detection." (PMID 42122194, 2026).
Portal vein thrombosis (1 paper, 2014). Thrombosis of the portal vein and/or its tributaries, which include the splenic vein and the superior and inferior mesenteric veins. "However, the expression of HSF1 was not correlated to HCC patient age, gender, HBV infection status, AFP expression levels, Ceacam1 expression levels and portal vein thrombosis." (PMID 25199534, 2014).
Shock (1 paper, 2013). The state in which profound and widespread reduction of effective tissue perfusion leads first to reversible, and then if prolonged, to irreversible cellular injury. "Meningococcal septic shock in children was associated with increased serum soluble CEACAM1." (PMID 23894299, 2013).
Splenomegaly (1 paper, 2009). Abnormal increased size of the spleen. "In contrast, during latency amplification, Ceacam1−/− mice displayed increased splenomegaly and a higher latent viral load in the spleen." (PMID 19621080, 2009). "At day 42 p.i., Ceacam1−/− mice still displayed increased splenomegaly." (PMID 19621080, 2009). "In summary, due to an altered immune response, Ceacam1−/− mice displayed an enhanced control of the acute lytic MHV-68 lung infection but elevated splenic viral loads and increased splenomegaly during latency amplification." (PMID 19621080, 2009). "Although Ceacam1−/− mice displayed an enhanced control of the acute lytic MHV-68 lung infection, the absence of CEACAM1 resulted in elevated viral loads and increased splenomegaly during latency amplification." (PMID 19621080, 2009). "Thus, the absence of CEACAM1 resulted in a more severe splenomegaly which could be due to increased proliferation and/or enhanced recruitment of cells." (PMID 19621080, 2009).
squamous intraepithelial lesions (1 paper, 2023). "In severe or high-grade squamous intraepithelial lesions (SIL) of patients with CC, the increased CEACAM-1 and TIM-3 interaction further suppresses the antitumor activity of CD4+ and CD8+ T cells." (PMID 37508372, 2023).